ESRRG (estrogen related receptor gamma)
Diseases named in the same sentence as ESRRG in open-access papers (continued):
Sharing a sentence is not in itself a finding about the gene and the disease.
tumor (continued). "Notably, the tumor suppressor role of DY131 significantly inhibited the expression of PKM2 in ESCC cells, confirming that the ESRRG agonist DY131 inhibited tumor proliferation by acting on the glycolysis pathway." (PMID 37679788, 2023). "Tumor Immune Dysfunction and Exclusion (TIDE) scores indicate sensitivity to immune checkpoint inhibitors; therefore, we evaluated differences in TIDE scores between the ESRRG high expression and low expression groups in the TCGA-ESCC dataset." (PMID 37679788, 2023). "These in vitro and in vivo findings indicate that ESRRG inhibits the proliferation of ESCC cells and may play a tumor-suppressive role in ESCC." (PMID 37679788, 2023). "High m6A methylation level in drug-resistant cells can trigger the splicing of ESRRG precurser, increases the expression of CPT1B and induces up-regulation of ERRγ in chemoresistant cells, which can promote fatty acid oxidation of tumor cells and enhance chemoresistance of tumor cells." (PMID 35022030, 2022). "Based on our network and the ceRNA mechanism, we speculated that LINC01128 might act as a tumor suppressor in MM through multiple mechanisms, including miR-142-5p/PARP9 or FAM133A axis, and the miR-299-3p/estrogen-related receptor gamma axis." (PMID 33193574, 2020). "In addition to the targets that we identified by RNA sequencing, miR-378a-5p has been shown to be involved in tumorigenesis and tumor maintenance by regulating SUFU, TUSC2, TOB2, GABPA and ESRRg." (PMID 24651706, 2014).
cancer (49 papers, 2013 to 2025). A tumor composed of atypical neoplastic, often pleomorphic cells that invade other tissues. "Estrogen-related receptor gamma (ERRγ), a nuclear receptor critical for cellular energy metabolism, has been implicated in various cancers." (PMID 40918468, 2025). "ESRRG expression was negatively associated with PFS in carcinoma categories including STES, STAD, and ACC." (PMID 40356747, 2025). "Considering the strong association between ESRRG expression and cancer prognosis and its crucial role in cell metabolism, ESRRG has emerged as a promising target for cancer diagnosis and therapy." (PMID 37679788, 2023). "Our pan-cancer analysis also reveals that the influence of ESRRG on immune cell infiltration is cancer-type specific." (PMID 40356747, 2025). "Further research is needed to elucidate ESRRG’s precise regulatory mechanisms and develop effective therapeutic strategies targeting ESRRG in cancer." (PMID 40356747, 2025). "By searching for this gene in our PETCH-DB database’s Cancer Biomarker Discovery, we confirmed that the ESRRG gene had higher 5hmC levels in HCC patients (i.e. cases), relative to the controls in an automatically generated box plot." (PMID 37387524, 2023). "The elevated Estrogen Related Receptor γ in chemoresistant cancer cells can be attributed to m6A-dependent splicing of precursor ESRRG mRNA." (PMID 37270544, 2023). "Previous studies have demonstrated the involvement of ESRRG in the regulation of metabolic reprogramming in various cancer cells." (PMID 37679788, 2023). "For instance, m6A upregulated estrogen-related receptor gamma (ERRγ) in chemo-resistant cancer cells." (PMID 36517820, 2022). "Our present findings thus demonstrate that ESRRG functions as a negative regulator of the Wnt signaling pathway in GC and is a potential therapeutic target for this cancer." (PMID 29765046, 2018). "Strikingly, the ESRRG agonist DY131 suppresses cancer growth and represses the expression of Wnt signaling genes." (PMID 29765046, 2018). "By knocking down ESRRG, we investigated whether those signaling pathways and key factors of the Protein-Protein Interaction (PPI) network identified by the pan-cancer analysis mediated the related biological functions of ESRRG." (PMID 40356747, 2025). "In addition to its importance in metabolic diseases, recent studies have demonstrated that ESRRG expression is correlated with clinical outcomes in various cancer types, drawing increasing attention from oncologists." (PMID 37679788, 2023). "Therefore, sophoridine can potentially become an effective ESRRG inducer to suppress cancer progression." (PMID 35269825, 2022). "In many cancers, ESRRG exhibits tumor suppressor activities." (PMID 35269825, 2022). "The upregulated ERRγ in chemoresistant cancer cells might be due to increased levels of N6-methyladenosine (m6A) can trigger the splicing of precursor ESRRG mRNA." (PMID 32206097, 2020). "Our present study thus provides new insights into the molecular mechanisms in GC, and suggests that activation of ESRRG by antagonizing Wnt signaling through compounds such as DY131 could provide a novel therapeutic approach to treating this cancer." (PMID 29765046, 2018). "How ESRRG is involved in cancer progression is thus worthy of further investigation." (PMID 29765046, 2018). "Since we found that ESRRG efficiently inhibited cancer cell growth by antagonizing Wnt signaling, we speculated that a pharmacological ESRRG agonist, DY131, might have efficacy as a suppressor of GC." (PMID 29765046, 2018).
cancer (continued). "The PPI network identified that ESRRG was significantly related to 20 genes, including PPARGC1A, PPARGC1B, MED1, CREBCF and so on, 6 of which were confirmed to be positively correlated with ESRRG expression by the XenaShiny TCGA Association Analysis module for single cancer." (PMID 40356747, 2025). "ESRRG has been identified as a tumor suppressor gene in several cancers, which is consistent with our findings that ESRRG is lowly expressed in HCC tissue and can predict the prognosis of HCC patients, indicating that ESRRG could regulate the occurrence and development of HCC." (PMID 34868990, 2021). "For example, in TCGA-BRCA, ESR1 is altered by mutation or expression in ∼10% of tumors, whereas other NRs (eg, NR5A2/LRH-1, ESRRG, NR1I3/CAR) are more frequently altered, and only a handful of cistromic datasets exist for these receptors across all cancers." (PMID 41150850, 2025). "In eight cancer types, including CHOL, there was a positive correlation found between the expression of PD-L1 and ESRRG." (PMID 40356747, 2025). "In most cancers, QUANTISEQ showed that ESRRG strongly contributed to the infiltration of natural killer cells and B cells, and weakened the infiltration of macrophages M1 and CD8+ T cells, promoting the formation of an immunosuppressive microenvironment." (PMID 40356747, 2025). "Our findings reveal that ESRRA predominantly acts as an oncogene in multiple cancer types, whereas ESRRB and ESRRG exhibit distinct roles across different tumors." (PMID 40356747, 2025). "For example, ESRRG and CEBPE interact with 15 and 5 cancer gene promoters, respectively, but interactions with our set of promoters were not reported in the literature nor in ChIP-seq experiments." (PMID 39013578, 2024). "First, we compared the fold change in expression of the ER-related receptors ESR1, ESR2, ESRRA, ESRRB, ESRRG, and GPER1 in the four female cancers." (PMID 38582811, 2024). "The expression patterns of estrogen and its related proteins, including estrogen-related receptor alpha (ESRRA), ESRRG, ER-alpha (ESR1), and ER-beta (ESR2), were examined in the HPA in different types of cancers." (PMID 37240447, 2023). "Hsa_circ_0002375, hsa_circ_0111974, and hsa_circ_0081534 are spliced from KIT ligand (KITLG), estrogen related receptor gamma (ESRRG), and EPH receptor B4 (EPHB4), respectively, which play an essential role in cancer proliferation, metastasis and apoptosis." (PMID 32426279, 2020). "Among the top 10 DRGs identified for Korean (GSE24375), six genes are GC related (ESRRG, LIMS1, GATA3, GATA6, SOX9, POU2F1) and the other four are cancer related (IRF2, RGS3, MRPL36, FOSB)." (PMID 29745833, 2018). "By our analysis, we have identified novel regions of allelic imbalance that contain several cancer related genes such as CHD1L and S100A9 at locus 1q21.1; and CENPF and ESRRG at locus 1q32-q42." (PMID 26314549, 2015). "A close positive correlation between ESRRG and CD160 was also found in predominant cancer types." (PMID 40356747, 2025). "Previous reports have implicated ESRRG in the pathophysiology of human breast, endometrial, and prostate cancer, but a detailed understanding of how ESRRG contributes to cancer progression is still lacking." (PMID 29765046, 2018). "With the exception of three clusters of NRs representing NR classes I (cluster I: RORC, VDR, PPARA, NR1D1, THRA, RORA, NR1H3; cluster II: RARB, PPARG, THRB) and III (cluster III: ESR1, PGR, AR, ESRRG), NR class was not a good determinate of NR expression patterns in the different cancer types." (PMID 32024906, 2020). "One study reported that increases in the m6A levels in ERRγ mRNA (estrogen receptor-related receptor) could trigger the splicing of precursor ESRRG mRNA to promote its expression, with the upregulation of ERRγ conferring chemoresistance to cancer cells through the upregulation of ABCB1 and CPT1B." (PMID 40000966, 2025).
cancer (continued). "As a result, the absence of RB1 disrupts the negative regulation of ESRRG by RB1, enabling cancer cells to survive under hypoxic stress." (PMID 38672640, 2024).
infection (7 papers, 2017 to 2022). The state of being infected such as from the introduction of a foreign agent such as serum, vaccine, antigenic substance or organism. "Recent evidence further suggest that an inverse agonist of estrogen related receptor gamma (ERRγ) is able to ameliorate Salmonella-induced hypoferremia by reduction of ERRγ-mediated hepcidin expression in hepatocytes leading to a better control of infection." (PMID 29329289, 2018). "After infection of adenovirus expressing canonical ESRRG and cryptic ESRRG, respectively, CCK-8 assay was performed to detect the effect of ESRRG on the proliferation." (PMID 32427851, 2020).
kidney disease (3 papers, 2023 to 2026). "Top healthy-promoting TFs included canonical PT TFs, HNF4A and PPARA, as well as other factors that have been demonstrated to be protective against kidney disease: ESRRG and RREB149,56–58." (PMID 38347009, 2024).
ESRRG also shares sentences with these, for which no sentence is quoted: metabolic disease (8 papers); heart failure (6); cardiomyopathy (5); diabetes (5); osteoarthritis (5); acute kidney injury (3); alcoholic fatty liver (3); diabetic cardiomyopathy (3); Insulin resistance (3); alcoholic liver damage (2); cholestasis (2); fatty liver disease (2); Glucose intolerance (2); Hypertension (2); hypertrophic cardiomyopathy (2); liver disease (2); myocarditis (2); Parkinson disease (2); abortion (1); alcohol (1); alcoholic cirrhosis (1); alcoholic hepatitis (1); anemia (1); Anxiety (1); atherosclerosis (1); atopic dermatitis (1); bacterial infection (1); breast ductal carcinoma (1); cardiac diseases (1); cardiac septal defects (1).
A further 46 diseases each share a sentence with ESRRG in 1 paper.